FIMP1 (fertilization-influencing membrane protein 1)
Description:
May play a role in sperm-oocyte fusion during fertilization.
Synonyms: FIMP; C16orf92; FLJ25404
Tractability: Antibody: UniProt places it where antibodies can reach, with medium confidence; UniProt predicts a signal peptide or a membrane-spanning region; its Gene Ontology location is reachable by antibodies, with medium confidence.
Gene: Protein-coding gene on chromosome 16 (30,023,198 to 30,027,736, forward strand). Ensembl gene ENSG00000167194.
Subcellular location: Cell membrane
Gene Ontology:
Molecular function: protein binding
Biological process: fertilization; fusion of sperm to egg plasma membrane involved in single fertilization
Cellular component: plasma membrane
Genetic constraint (gnomAD): Loss-of-function variants: 14 observed, 13.46 expected, observed/expected ratio (o/e) 1.04, 90% interval 0.69 to 1.61. The upper end of that interval is the gene's LOEUF score, 1.61, which puts it in group 6 of 6, group 1 being the genes least tolerant of losing a copy. Missense variants: 116 observed, 145.42 expected, observed/expected ratio (o/e) 0.8, 90% interval 0.69 to 0.93. Synonymous variants: 50 observed, 59.57 expected, observed/expected ratio (o/e) 0.84, 90% interval 0.67 to 1.06.
Homologues: Orthologues: chimpanzee C16H16orf92 (84% identical), macaque C6H16orf92 (80% identical), pig C16orf92 (65% identical), mouse 4930451I11Rik (61% identical), dog C16orf92 (57% identical), guinea pig C16orf92 (57% identical).
Diseases named in the same sentence as FIMP1 in open-access papers:
FIMP1 is named in the same sentence as 2 diseases in open-access papers, as found by Europe PMC text mining. Sharing a sentence is not in itself a finding about the gene and the disease.
FIMP1 shares sentences with these, for which no sentence is quoted: Infertility (2 papers); male infertility (1).